RN7SL545P (RNA, 7SL, cytoplasmic 545, pseudogene)
Gene: Miscellaneous RNA gene on chromosome 15 (22,429,200 to 22,429,489, reverse strand). Ensembl gene ENSG00000274568.
Homologues: Orthologues: pig Metazoa_SRP (54% identical), macaque Metazoa_SRP (48% identical). Paralogues in human: RN7SL759P (100% identical), RN7SL536P (99% identical), Metazoa_SRP (99% identical), RN7SL106P (99% identical), RN7SL238P (99% identical), RN7SL196P (88% identical), RN7SL286P (88% identical), RN7SL539P (88% identical), RN7SL796P (88% identical), RN7SL214P (79% identical), RN7SL736P (79% identical), RN7SL209P (78% identical), and 702 more.